PDGFRB (platelet derived growth factor receptor beta)
Diseases named in the same sentence as PDGFRB in open-access papers (continued):
Sharing a sentence is not in itself a finding about the gene and the disease.
brain injuries (4 papers, 2018 to 2024). "Perivascular cells expressing platelet-derived growth factor receptor beta (PDGFR-β) have recently been implicated in fibrotic scar formation after acute brain injury, but their precise identity and detailed morphological characteristics remain elusive." (PMID 30455628, 2018). "In addition, we found that early reperfusion increased the number of PDGFRβ+ pericytes, which are associated with wound healing following brain injuries." (PMID 32492968, 2020).
Castleman disease (4 papers, 2022 to 2025). Castleman disease (CD) is a benign lymphoproliferative disorder that may present as a localized or multicentric form. "In Castleman disease, improper ETS1, PTPN6, TGFBR2, DNMT3A, and PDGFRB genes cause the appearance of symptoms." (PMID 36766791, 2023).
ductal carcinoma in situ (4 papers, 2021 to 2025). "For example, high stromal PDGFRβ expression was identified as a novel biomarker for predicting radiosensitivity in ductal carcinoma in situ (DCIS)." (PMID 40384989, 2025).
esophageal cancer (4 papers, 2017 to 2025). A primary or metastatic malignant neoplasm involving the esophagus. "The overexpression of FN1 or PDGFRB also enhanced the cell proliferation and migration ability, highlighting the importance of these two gene in esophageal cancer cells proliferation/invasion although the underlying mechanisms remains unknown." (PMID 28147311, 2017). "FN1 and PDGFRB are highly expressed in human esophageal cancer and play significant roles in promoting cell proliferation and migration." (PMID 40071088, 2025). "• Upregulates fibronectin 1 (FN1) and platelet-derived growth factor receptor beta (PDGFRB) in esophageal cancer." (PMID 40071088, 2025). "Network analysis and functional experiments further identified FN1 and PDGFRB to be key downstream genes regulated by SATB1 in esophageal cancer cells." (PMID 28147311, 2017). "To further explore the clinical significance of FN1 and PDGFRB expression in human esophageal cancer patients, we performed the online database analysis (Oncomine) to examine their expressions in human esophageal cancer patients." (PMID 28147311, 2017). "Importantly, FN1 and PDGFRB were found to be highly expressed in human esophageal cancer." (PMID 28147311, 2017). "In conclusion, SATB1 is an oncogenic gene involved in esophageal cancer tumor cell proliferation and metastatic potential regulation; its function is partially delivered by the downstream genes FN1 and PDGFRB." (PMID 28147311, 2017). "In summary, we provided the first molecular evidence that SATB1 played an oncogenic role in esophageal cancer by up-regulation of FN1 and PDGFRB." (PMID 28147311, 2017). "MiR-30b-5p inhibits the migration and invasion of esophageal cancer by targeting ITGA5 and PDGFRb." (PMID 34819077, 2021).
hemangioma (4 papers, 2017 to 2025). A benign vascular lesion characterized by the formation of capillary-sized or cavernous vascular channels. "The expression of CD146 mostly overlapped with that of PDGFRβ in proliferative hemangioma." (PMID 37182177, 2023). "They proved that PDGFB and PDGFRβ signaling plays a role in hemangioma pathogenesis." (PMID 33400686, 2021). "In addition, data from a separate study demonstrated that PDGFB and PDGFRβ signaling might act as an intrinsic negative regulator of hemangioma involution." (PMID 33400686, 2021). "PDGFRβ was not expressed in HemMCs in involuting hemangioma." (PMID 37182177, 2023).
intimal sarcoma (4 papers, 2017 to 2024). A malignant neoplasm arising from the large blood vessels. "This case report illustrates the complexities and evolving nature of cardiac intimal sarcoma treatment, emphasizing the potential of PDGFRβ signaling as a strategic target and highlighting the importance of adapting treatment pathways in response to genetic shifts." (PMID 38646431, 2024).
intracerebral hemorrhage (4 papers, 2021 to 2025). A cerebrovascular disorder characterized by bleeding into one or both cerebral hemispheres including the basal ganglia and the cerebral cortex. "PDGF-D has been reported to promoting the infiltration of PDGFRβ+ macrophages in an experimental model of intracerebral hemorrhage." (PMID 38769116, 2024). "In the brains of mice, intra-ipsilateral and contralateral infusion of the PDGFRβ inhibitor Greevec decreases the intracerebral hemorrhage-induced increase in TNF-α levels." (PMID 34122447, 2021).
Kosaki overgrowth syndrome (4 papers, 2022 to 2025). "PDGFRB germline variants with a higher constitutive activity, such as p.P584R or p.W566R, have been identified in patients with Kosaki overgrowth syndrome, who exhibit alterations in bones, the brain and the skin." (PMID 35689379, 2022). "Germline PDGFRB variants may cause Penttinen or Kosaki overgrowth syndrome, but variants associated with these conditions overactivate PDGFRB more potently than those linked to familial IM." (PMID 40632343, 2025). "In addition, although it remains to be formally shown that activating mutations of PDGFRβ in osteoprogenitors contributes to osteopenia and occurrence of fractures in patients with Penttinen syndrome or Kosaki overgrowth syndrome, Scl-Ab could be useful to treat those pathological conditions." (PMID 38713511, 2024).
oligodendroglioma (4 papers, 2009 to 2013). A well-differentiated (WHO grade II), diffusely infiltrating neuroglial tumor, typically located in the cerebral hemispheres. "Platelet-derived growth factor (PDGF) and the PDGF receptors, PDGFRα and PDGFRβ, are overexpressed in the majority of oligodendrogliomas." (PMID 24023893, 2013).
pancreatic ductal adenocarcinoma (4 papers, 2019 to 2023). An infiltrating adenocarcinoma that arises from the epithelial cells of the pancreas.
rheumatoid arthritis (4 papers, 2011 to 2024). A chronic, systemic autoimmune disorder characterized by inflammation in the synovial membranes and articular surfaces. "Another similar drug imatinib has shown promise in treating rheumatoid arthritis in mouse models and specific patients, speculated due to its inhibition of mast cell c-Kit and PDGFRB." (PMID 21909252, 2011).
thrombosis (4 papers, 2010 to 2023). "Recent studies have found PDGFRB to be closely associated with thrombosis and IS." (PMID 37794518, 2023).
Wilms tumor (4 papers, 2019 to 2025). An embryonal neoplasm characterized by the presence of epithelial, mesenchymal, and blastema components. "Moreover, research has indicated that dual inhibition of FAK and platelet-derived growth factor receptor-beta (PDGFR-β) synergistically decreases the survival of primary Wilms tumor cells, suggesting potential applications in pediatric renal tumors." (PMID 39976799, 2025).
amyloid (3 papers, 2020 to 2025). "Retinal vascular changes in murine AD models were apparent at younger ages of 4 and 8 months and tightly correlated with severity of retinal pericyte biomarker (PDGFRβ) deficiency, suggesting pericyte loss occurs early in the retina of amyloidosis-derived AD models." (PMID 33228786, 2020). "Interestingly, the association observed between CSF PDGFRβ levels and CSF YKL-40 and sTREM2 was independent of markers of amyloid pathology, which has already been described." (PMID 40239464, 2025).
Arthritis (3 papers, 2021 to 2023). Inflammation of a joint. "Thus, we used an experimental model of RA; zymosan was injected into the knee joints of PDGFRb-CreERT2 × ROSA26 td-Tomato mice to induce arthritis with the aim of tracking the pericytes in synovial joints." (PMID 33536212, 2021). "Additionally, mononuclear preosteoclasts expressed high levels of PDGF‐BB in a murine model of arthritis, which recruited pericytes for neovessel formation by activating PDGF‐BB/PDGFRβ signalling." (PMID 36694343, 2023). "Lineage tracing of perivascular cells with inducible PDGFRβ and NG2 Cre mouse lines demonstrated that increased pericyte to fibroblast differentiation distinguishes injury-induced organ fibrosis and zymosan-induced arthritis." (PMID 33536212, 2021).
cerebral amyloid angiopathy (3 papers, 2021 to 2024). "These authors also noted an association between retinal vascular platelet-derived growth factor receptor-β (PDGFRβ) expression and greater pericyte loss along with retinal vascular amyloidosis and cerebral amyloid angiopathy in MCI and AD patients." (PMID 38633534, 2024). "Importantly, we recently identified early and progressive deficiency in retinal vascular platelet-derived growth factor receptor-β (PDGFRβ) expression and pericyte loss that were associated with retinal vascular amyloidosis and cerebral amyloid angiopathy in MCI and AD patients." (PMID 34630020, 2021).
cystitis (3 papers, 2021 to 2022). Inflammation of the urinary bladder. "Prior studies have demonstrated increased expression of total PDGFRβ protein in UC tumors compared to tissues from dogs with normal or polyploid cystitis; however, in these studies the phosphorylation status was not evaluated." (PMID 34600548, 2021).
endothelial dysfunction (3 papers, 2024 to 2025). In vascular diseases, endothelial dysfunction is a systemic pathological state of the endothelium (the inner lining of blood vessels) and can be broadly defined as an imbalance between vasodilating and vasoconstricting substances produced by (or acting on) the endothelium. "Pericytes showed impaired features including low PDGFRβ expression and increased pro-inflammatory chemokines secretion under the administration of Aβ in vitro, of which supernatant cultured with bEND.3 cells led to significant endothelial dysfunction characterized by TJ protein deficiency." (PMID 38475929, 2024).
eosinophilic disorders (3 papers, 2013 to 2025). "Cytogenetic testing was negative for PDGFRA, PDGFRB, and FGFR1 mutations, ruling out clonal eosinophilic disorders." (PMID 40823575, 2025). "Unlike clonal eosinophilic disorders secondary to PDGFRA and PDGFRB translocations, the WHO-defined CEL-NOS entity is not responsive to imatinib mesylate monotherapy." (PMID 24224106, 2013).
Focal cortical dysplasia (3 papers, 2021 to 2024). A type of malformation of cortical development that primarily affects areas of neocortex. "Similarly, brain specimens derived from epileptic subjects affected by intractable seizures associated with focal cortical dysplasia displayed high perivascular PDGFRβ immunoreactivity—typical of pericytes—and revealed ramified PDGFRβ-positive cells proximal to microvessels." (PMID 38338969, 2024). "However, perivascular PDGFRβ+ pericytes are elevated in conditions like focal cortical dysplasia (FCD) or temporal lobe epilepsy with hippocampal sclerosis (TLE-HS)." (PMID 39479522, 2024). "With the advent of PDGFRβ, though a nonspecific CNS pericyte marker, the immunostaining reports of the presence of PDGFRβ+ cells have emerged in the brain specimens of patients with intractable epilepsy in focal cortical dysplasia (FCD) and temporal lobe seizures (TLE)." (PMID 34209145, 2021).
glomus tumor (3 papers, 2017 to 2025). A rare benign or malignant mesenchymal neoplasm arising from cells that resemble the modified smooth muscle cells of the glomus body. "In perivascular soft tissue tumors, a reduced expression of αSMA, CD146, and PDGFRβ in pericytes from malignant glomus tumors has been implicated in partial loss of pericytic differentiation." (PMID 28553358, 2017). "Familial occurrences of glomus tumors suggest a genetic predisposition, with mutations in genes such as NOTCH3 and PDGFRB implicated in some cases, though the complete genetic landscape remains incompletely understood." (PMID 39776317, 2025). "Approximately 6% of glomus tumors with uncertain malignant potential exhibit the BRAF V600E mutation, and the majority are positive for PDGFRB staining." (PMID 39776317, 2025). "Recent reports have identified PDGFRB and NOTCH3 mutations as characteristics of myopericytoma; however, these mutations have also been observed in angioleiomyoma and glomus tumors, suggesting that they are not useful for differential diagnosis." (PMID 40599523, 2025).
intrahepatic cholangiocarcinoma (3 papers, 2021 to 2023). A carcinoma that arises from the intrahepatic bile duct epithelium in any site of the intrahepatic biliary tree. "Multiplex-IF of intrahepatic cholangiocarcinoma revealed stromal protein gradients similar to those observed in CRLM, which were characterized by ASMA, NGFR, and PDGFRa at the outer edge, and FAP and PDGFRb at the inner side of the rim." (PMID 37596278, 2023).
invasive carcinoma (3 papers, 2008 to 2018). A carcinoma that is not confined to the epithelium, and has spread to the surrounding stroma. "Paraffin sections of three invasive carcinomas (cases 1–3) were triple immunostained with antibodies targeting αSMA, HLA-DR, and PDGFRβ." (PMID 30272010, 2018).
keloid (3 papers, 2022 to 2024). An irregularly shaped, elevated mark on the skin caused by deposits of excessive amounts of collagen during wound healing. "Moreover, in our current research, we observed that TEM1 silencing in keloid fibroblasts (KFs) led to notable effects, including a decrease in the phosphorylation of ERK and AKT, as well as a reduction in PDGFRβ protein expression induced by PDGF-BB." (PMID 38254097, 2024). "PDGFRL may show a redundant function or a differential function with PDGFRB; thus, PDGFRL may also be a potential therapeutic target of keloids." (PMID 35435317, 2022).
multiple sclerosis (3 papers, 2024 to 2025). A progressive autoimmune disorder affecting the central nervous system resulting in demyelination. "Deepak discovered that in brain sections of Multiple Sclerosis (MS) patients, Platelet-Derived Growth Factor Receptor Beta (PDGFRβ+) cells migrated into the perivascular space." (PMID 40295513, 2025).
Myocardial fibrosis (3 papers, 2016 to 2025). "Quantitative PET readouts of PDGFRβ expression may ultimately serve as both a diagnostic biomarker and a pharmacodynamic endpoint in clinical trials targeting myocardial fibrosis." (PMID 41471324, 2025).
ovarian tumors (3 papers, 2011 to 2025). "Altogether, our results indicate that PDGFRβ could play a relevant role in the dissemination capacity of ovarian tumor cells." (PMID 38010623, 2024).
pericardial effusion (3 papers, 2021 to 2024). Fluid collection within the pericardial sac, usually due to inflammation. "It has been suggested that dasatinib provokes serositis (PE and/or pericardial effusion) by causing inhibition of PDGFR beta (PDGFRβ) or Src family kinases, leading to decrease in interstitial fluid pressure or increase endothelial permeability, respectively." (PMID 38558869, 2024).
plexiform neurofibroma (3 papers, 2013 to 2023). An elongated and multinodular neurofibroma, formed when the tumor involves either multiple trunks of a plexus or multiple fascicles of a large nerve, such as the sciatic. "However, imatinib mesylate, an oral kinase inhibitor targeting c-kit and PDGFRβ, was recently reported to decrease plexiform neurofibromas by 20% or more in 6 out of 36 NF1 patients in a phase 2 trial." (PMID 25026295, 2014).
serous adenocarcinoma (3 papers, 2011 to 2013). An adenocarcinoma that is characterized by the presence of papillary patterns and cellular budding. "The 2-week treatment with sunitinib reduced tyrosine phosphorylation of VEGFR2 and PDGFRβ in both the serous carcinoma (LTL247) and CCOC (LTL175) tissues to very low levels." (PMID 21754983, 2011).
spinal cord injury (3 papers, 2021 to 2024). Penetrating and non-penetrating injuries to the spinal cord resulting from traumatic external forces (e.g., WOUNDS, GUNSHOT; WHIPLASH INJURIES; etc.). "Platelet derived growth factor receptor β positive (PDGFRβ+) pericytes form fibrotic scar, which prevents axonal regeneration after spinal cord injury (SCI)." (PMID 33935795, 2021). "In the context of spinal cord injury (SCI), infiltrating macrophages assume prominence as the primary inflammatory cells within the lesion core, where the fibrotic scar is predominantly orchestrated by platelet-derived growth factor receptor beta (PDGFRβ+) fibroblasts." (PMID 39407295, 2024).
thymic carcinoma (3 papers, 2017 to 2023). Thymic carcinoma (TC) is a type of thymic epithelial neoplasm characterized by a high malignant potential. "Immunohistochemistry was performed to study the expression of ALK, HER2, HER3, MET, phospho-mTOR, p16INK4A, PDGFRA, PDGFRB, PD-L1, PTEN and ROS1 in type A and B3 thymomas and thymic carcinomas." (PMID 27844328, 2017). "Type A and B3 thymoma and thymic carcinoma tissues were stained with antibodies to ALK, HER2, HER3, MET, phospho-mTOR, PDGFRA, PDGFRB, PD-L1, p16INK4A, PTEN and ROS1 to identify potential targets for therapy." (PMID 27844328, 2017). "A weak PDGFRB positivity was present in a few type A and B3 thymomas, whereas all thymic carcinomas were negative." (PMID 27844328, 2017).
vascular malformation (3 papers, 2022 to 2025). A non-neoplastic disorder that is the result of defects of vascular morphogenesis. "This study shows that the Pdgfrβ F7 mutation alone induces vascular malformations by increasing pro-angiogenic gene expression and suppressing TGFβ1 signaling." (PMID 41001557, 2025). "Taken together, our findings establish a mechanistic link between PDGFRβ mutation and the development of vascular malformations, highlighting the critical interplay between pericyte recruitment, angiogenic signaling, and inflammatory processes in bAVM pathogenesis." (PMID 41001557, 2025). "Overexpression of ALK1 in brain endothelial cells (ECs) reduces angiogenic signaling and the severity of vascular malformations in Pdgfrβ mutant mice." (PMID 41001557, 2025). "Thus, PDGFRB mosaicism appears to account for the patient’s myofibromas and capillary malformations, supporting a broad spectrum of PDGFRB-driven anomalies ranging from myofibromas to vascular malformations." (PMID 40632343, 2025).
anaplastic large cell lymphoma (2 papers, 2022 to 2024). Anaplastic large cell lymphoma (ALCL) is a rare and aggressive peripheral T-cell non-Hodgkin lymphoma, belonging to the group of CD30-positive lymphoproliferative disorders, which affects lymph nodes and extranodal sites. "Furthermore, STAT5 activation is targetable in cutaneous T cell lymphomas, bearing STAT5A and STAT5B copy number gains, and PDGFRβ-driven anaplastic large cell lymphoma." (PMID 38618957, 2024).
bladder tumors (2 papers, 2023). "High expression of FAP and CD90 expressed by fibroblasts as well as platelet-derived growth factor receptor beta (PDGFRb) were furthermore correlated with higher grade of bladder tumour." (PMID 36928373, 2023).
Blindness (2 papers, 2010 to 2020). Blindness is the condition of lacking visual perception defined as a profound reduction in visual perception. "A mechanism whereby loss of Arf enhances Pdgf signaling, resulting in an excessive proliferation and accumulation of Pdgfrβ+ perivascular cells was proposed to explain the vascular defect resulting in blindness in Arf−/− mice." (PMID 20805995, 2010).
CADASIL (2 papers, 2015 to 2020). "To elucidate the effect of increased PDGFRβ and its involvement in CADASIL pathogenesis, we cultured control and CADASIL MCs in serum-free medium with increasing concentration of PDGF-BB and compared their proliferation rate." (PMID 32188464, 2020).
calcification (2 papers, 2022 to 2024). Process by which organic tissue becomes hardened by the physiologic deposit of calcium salts. "For example, primary familial brain calcification has recently been linked to heterozygous mutations in PDGFRB gene." (PMID 35615282, 2022).